TCF23 (transcription factor 23)
Description:
Inhibits E-box-mediated binding and transactivation of bHLH factors. Inhibitory effect is similar to that of ID proteins. Inhibits the formation of TCF3 and MYOD1 homodimers and heterodimers. Lacks DNA binding activity. Seems to play a role in the inhibition of myogenesis (By similarity).
Synonyms: TCF-23; bHLHa24; OUT
Tractability: No criterion of Open Targets' tractability assessment is met for any kind of drug.
Gene: Protein-coding gene on chromosome 2 (27,149,004 to 27,156,974, forward strand). Ensembl gene ENSG00000163792.
Subcellular location: Nucleus
Subcellular location (Human Protein Atlas): Nuclear speckles
Gene Ontology:
Molecular function: protein binding; DNA-binding transcription factor activity, RNA polymerase II-specific; RNA polymerase II transcription regulatory region sequence-specific DNA binding; RNA polymerase II-specific DNA-binding transcription factor binding; transcription regulator inhibitor activity; protein dimerization activity
Biological process: decidualization; positive regulation of gene expression; developmental process; negative regulation of muscle cell differentiation; negative regulation of transcription by RNA polymerase II; regulation of transcription by RNA polymerase II
Cellular component: chromatin; euchromatin; nucleus
Genetic constraint (gnomAD): Loss-of-function variants: 7 observed, 11.22 expected, observed/expected ratio (o/e) 0.62, 90% interval 0.35 to 1.17. The upper end of that interval is the gene's LOEUF score, 1.17, which puts it in group 5 of 6, group 1 being the genes least tolerant of losing a copy. Missense variants: 257 observed, 276.41 expected, observed/expected ratio (o/e) 0.93, 90% interval 0.84 to 1.03. Synonymous variants: 122 observed, 118.15 expected, observed/expected ratio (o/e) 1.03, 90% interval 0.89 to 1.2.
Homologues: Orthologues: chimpanzee TCF23 (100% identical), macaque TCF23 (97% identical), pig TCF23 (81% identical), guinea pig TCF23 (79% identical), mouse Tcf23 (77% identical), dog TCF23 (77% identical), rat Tcf23 (74% identical), zebrafish tcf23 (35% identical), Drosophila melanogaster HLH54F (17% identical), Drosophila melanogaster twi (15% identical), Drosophila melanogaster Hand (14% identical), Drosophila melanogaster CG33557 (14% identical), and 1 more. Paralogues in human: TCF24 (36% identical), MSC (21% identical), TCF21 (21% identical), SCX (20% identical), TCF15 (18% identical), HAND1 (18% identical), HAND2 (17% identical), PTF1A (17% identical), BHLHA9 (16% identical), FIGLA (16% identical), TWIST2 (16% identical), TWIST1 (15% identical), and 1 more.
Diseases named in the same sentence as TCF23 in open-access papers:
TCF23 is named in the same sentence as 1 disease in open-access papers, as found by Europe PMC text mining. Sharing a sentence is not in itself a finding about the gene and the disease.
TCF23 shares sentences with these, for which no sentence is quoted: essential hypertension (1 paper).